MMP2 (matrix metallopeptidase 2)
Diseases named in the same sentence as MMP2 in open-access papers (continued):
Sharing a sentence is not in itself a finding about the gene and the disease.
hidradenitis suppurativa (2 papers, 2024 to 2025). A chronic suppurative and cicatricial disease of the apocrine glands occurring chiefly in the axillae in women and in the groin and anal regions in men. "MIR132 heightens inflammation and pain sensitivity, while matrix metalloproteinases (MMPs), specifically MMP-2 and MMP-3, significantly impact the pathogenesis of hidradenitis suppurativa (HS)." (PMID 39940809, 2025). "Variants involved the TLR2 and MPO genes in the first family and the MMP2, GJB2, and TLR4 genes, some of which have already been previously reported as possible candidates for hidradenitis suppurativa." (PMID 39595064, 2024).
HIV-1 infection (2 papers, 2019 to 2022). The type species of lentivirus and the etiologic agent of acquired immunodeficiency syndrome (AIDS). "The second study assessed the neuroinflammatory effect of HIV-1 infection in brain tissue, which was characterized by its sudden onset and increase in activity and expression of MMP-2 and MMP-9." (PMID 35743229, 2022). "While a limitation of the study were the small number of cases, the study demonstrates that maternal HIV-1 infection might not have a dramatic influence on placental IGF1, IGFBP1, MMP2, MMP9, ANG1, ANG2 and Gal-13 levels in Cameroonian pregnant normotensive women with majority receiving cART." (PMID 31042729, 2019).
incontinence (2 papers, 2022 to 2025). "There is also in vivo data on the implication of ECM-degrading enzymes in incontinence, as increased MMP-2 and MMP-9 activity was reported in the vaginal wall after VD." (PMID 36742196, 2022). "The expression of MMP2 was upregulated in patients with urinary incontinence (P<0.001, 95%CI = 0.49–0.63), and a negative correlation existed between MMP2 and miR-330-3p levels in these patients (r= -0.7431, P<0.001, 95%CI= -0.85 to -0.58)." (PMID 40533843, 2025).
insomnia (2 papers, 2016 to 2020). A sleep disorder characterized by difficulty in falling asleep and/or remaining asleep. "This is the first longitudinal study to examine linkages between symptoms, HSCs, and cytokines, demonstrating that fatigue and insomnia shared associations with increasing serum levels of IP-10 and TNF-RII, and mental fatigue was associated with increasing serum levels of MMP-2." (PMID 33134822, 2020).
Japanese encephalitis (2 papers, 2016 to 2022). A disease due to a virus transmitted by an arthropod). "In the case of ZO-1, Japanese encephalitis viral infected astrocytes induce the expression of VEGF, IL-6, and MMP2/MMP-9 that upregulate the expression of the E3-Ub-ligase component n-recognin-1 that triggers ZO-1 ubiquitination and degradation." (PMID 36291162, 2022).
juvenile idiopathic arthritis (2 papers, 2019 to 2021). Juvenile idiopathic arthritis (JIA) is the term used to describe a group of inflammatory articular disorders of unknown cause that begin before the age of 16 and last over 6 weeks. "The characteristic radiological signs combined with symptoms resembling juvenile idiopathic arthritis (JIA) set the diagnosis, which is established either by measuring matrix metalloproteinase-2 (MMP-2) enzyme activity through electrophoresis (zymography) or genomic testing." (PMID 34466312, 2021). "The aim of this study was to evaluate the concentration of MMP-2, MMP-8, and MMP-9 and their inhibitors TIMP-1 and TIMP-2 of unstimulated whole saliva (UWS) in correlation with the oral health in juvenile idiopathic arthritis (JIA) children." (PMID 31781639, 2019).
kidney injury (2 papers, 2021 to 2022). Trauma to the kidney. "Additionally, several studies have shown that inhibition of MMP-2 and MMP-9 protects against AKI, as they are increased in the acute phase of kidney injury and modulate tubular/microvascular damage." (PMID 35629096, 2022).
Knee Osteoarthritis (2 papers, 2024). "However, in a study of patients with knee osteoarthritis, a reduction in pro-inflammatory molecules (MMP-2, IL-1B, IL-6, and IL-8) and an increase in anti-inflammatory molecules (IGF-1 and IL-10) were found at the 1-year follow-up after an SVF injection." (PMID 38391657, 2024).
limb ischemia (2 papers, 2011 to 2019). A ischemia that involves the limb. "After 3 days of limb ischemia following femoral artery ligation, MMP-2, MMP-3, and MMP-13 were increased in diabetic mice compared to controls, but collagenolysis was decreased, indicating a suppression of the response." (PMID 22214528, 2011).
lumbar disc degeneration (2 papers, 2012 to 2021). "A polymorphism in the promoter of MMP-1, MMP-2, MMP-3, and MMP-9 genes, which enhance promoter activity, is associated with a higher prevalence of lumbar disc degeneration in Japanese elderly patients and Chinese adult cohorts." (PMID 22394620, 2012). "MMP-2 (matrix metalloproteinase-2) takes part in the pathophysiology of lumbar disc disease." (PMID 33494410, 2021).
lymphedema (2 papers, 2017 to 2024). Excess fluid collection in tissues, causing swelling. "With destruction/remodeling of the vessel architecture, here hypothesized to be in part caused by MMP-2, lymph fluid enters the surrounding tissue causing lymphedema." (PMID 29122006, 2017). "At the sametime, such combinations of genotypes as VEGF-2578 CA:VEGF+936 TT: MMP9-1562 CT and VEGF-2578 CA:VEGF+936 TT: MMP2-1306 CC: MMP9-1562 CT were notfound among representatives of the group of healthy individualsand were identified exclusively among patients withprimary lymphedema." (PMID 39027126, 2024). "Changes in the frequency distribution of MMP2 genotypes in primary and MMP3 in secondary lymphedema are shown." (PMID 39027126, 2024).
male infertility (2 papers, 2018 to 2022). The inability of the male to effect fertilization of an ovum after a specified period of unprotected intercourse. "Further studies should be performed with larger sample size together with the determination of MMP-9 and MMP-2 activities to provide more information about the impact of these polymorphisms on male infertility." (PMID 29043698, 2018). "We analyzed the synergism of genotypes and alleles of G-1575A MMP-2 and C-1562T MMP-9 gene polymorphisms on male infertility." (PMID 29043698, 2018). "In addition, a relationship was observed between combined MMP-2 and MMP-9 variant genotypes and male infertility." (PMID 29043698, 2018).
metastatic colorectal cancer (2 papers, 2021 to 2024). "The role of matrix metalloproteinase-2 (MMP-2) in tumor cell migration has been widely studied, however, the characteristics and effects of MMP-2 in clinical sample of metastatic colorectal cancer (CRC) remain poorly understood." (PMID 34429501, 2021). "Furthermore, by using integrated proteomics analyses, increased production of MMP‐2 and integrin complexes mediated by activation of focal adhesion kinase (FAK) signalling has been shown to contribute to the high aggressiveness of metastatic colorectal cancer." (PMID 39121240, 2024).
Moyamoya disease (2 papers, 2014 to 2021). Moyamoya disease (MMD) is a rare intracranial arteriopathy involving progressive stenosis of the cerebral vasculature located at the base of the brain causing transient ischemic attacks or strokes. "ROC analysis revealed the optimal cut-off value for MMP-2 as 1.5 ng/mL, which is associated with a sensitivity of 0.88 or 88% (28 of 32 moyamoya disease patients correctly classified), a specificity of 1.00 or 100% (all 14 controls correctly classified), and an accuracy of 91% (42/46)." (PMID 33868159, 2021). "A total of 88% of moyamoya disease patients were positive for MMP-2 (28 of 32) compared to 0 of 14 controls (P < 0.001)." (PMID 33868159, 2021). "Any non-zero cut-off value or criterion for MMP-2 would have produced false negatives since four moyamoya disease patients did not have measurable MMP-2 in their urine." (PMID 33868159, 2021). "Multiple stepwise logistic regression revealed that, independent of age and gender, urinary MMP-2 was the only independent biomarker that significantly differentiates moyamoya disease patients from controls (c-index = 0.938, P < 0.001)." (PMID 33868159, 2021).
mucopolysaccharidoses (2 papers, 2020 to 2024). "Elevated levels of MMP-2 and decreased levels of MMP-9 have also been observed in patients with mucopolysaccharidosis (MPS), suggesting that altered MMP expression may contribute to joint/bone abnormalities in other lysosomal storage disorders." (PMID 39590837, 2024).
obstructive sleep apnea (2 papers, 2015 to 2021). "In fact, plasma MMP9 levels are elevated in patients with obstructive sleep apnea, and urinary MMP2 activity has been shown to increase in accordance with obstructive sleep apnea severity." (PMID 34512381, 2021).
oral diseases (2 papers, 2024). "Accurate detection of matrix metalloproteinase-2 (MMP-2) is crucial for the early diagnosis, prognosis, and treatment of oral diseases." (PMID 39554809, 2024). "As DDR1 has been verified to be significant in the development of dental and periodontal tissues and the process of oral diseases, in the present study, we focused on the mechanisms controlling DDR1-mediated MMP-1, MMP-2, and MMP-13 expression in hPDLCs to demonstrate the role of DDR1 in ERR." (PMID 39596178, 2024).
oral submucous fibrosis (2 papers, 2021 to 2025). "In contrast, in our study on naringenin's antifibrotic effects in oral submucous fibrosis (OSMF) focuses on molecular targets such as MMP2, MMP3, MMP9, TGFB1, ESR1, and SERPINE1, which are crucial in ECM remodeling and inflammation." (PMID 40575446, 2025).
oro-pharyngeal cancers (2 papers, 2017 to 2019). "The microarray analysis of oro-pharyngeal cancers indicated increased levels of MMP1, but not MMP2, 9 and 14 in these tumours compared to normal tissue suggesting a potentially important role of MMPs in invasion." (PMID 26001294, 2017).
orofacial cleft (2 papers, 2021 to 2022). A disorder of facial skeleton that is characterized by cleft lip and/or cleft palate that result in feeding, speech and hearing problems caused by failures during development. "Although evidence from both animal and human studies support a role for MMP2 as a candidate gene in the occurrence of nonsyndromic orofacial clefts, only one study has explored its genetic variants in NSCL±P risk." (PMID 36661544, 2022).
Osteolysis (2 papers, 2019 to 2020). Osteolysis refers to the destruction of bone through bone resorption with removal or loss of calcium. "Some patients present with nodulosis, arthropathy, and osteolysis (NAO syndrome) as a result of a mutation in the matrix metalloproteinase 2 (MMP2) gene." (PMID 32894151, 2020).
otitis media (2 papers, 2012 to 2022). Inflammation of the anatomical structures of the middle ear, which is most often caused by an infectious process. "The activity of MMP2 is also hypothesized to be involved in destruction of the TM fibrous layer and the prognosis of otitis media." (PMID 34859918, 2022).
ovarian serous cystadenocarcinoma (2 papers, 2021 to 2022). A malignant serous cystic epithelial neoplasm arising from the ovary. "Besides, STAT5A was negatively related to tumor-promoting MMP2 expression in human ovarian serous cystadenocarcinoma cell line HO8910." (PMID 36524006, 2022).
papilloma (2 papers, 2015 to 2019). A benign epithelial neoplasm that projects above the surrounding epithelial surface and consists of villous or arborescent outgrowths of fibrovascular stroma. "We validated by qRT-PCR the upregulation of EMT drivers, such as Zeb1, Zeb2, Twist and Prrx1, and EMT mediators, such as Wnt5a, Vcan, Ncadh and Mmp2 both in Nanog-papillomas and in Nanog-SCCs." (PMID 25988972, 2015).
peritonitis (2 papers, 2019 to 2021). Inflammation of the peritoneum (tissue that lines the abdominal wall and covers most of the organs in the abdomen). "MMP-2 levels can also be affected by chronic inflammation or other infections in the peritoneum, including peritonitis." (PMID 33532492, 2021). "MMP-2 was associated with chemical peritoneal injury and showed increased levels in PD effluent in patients with peritoneal injury, while PD effluent levels of MMP-9 and TIMP-1 were higher in the onset of peritonitis." (PMID 31815017, 2019).
pituitary apoplexy (2 papers, 2018 to 2022). A rare, potentially life-threatening disorder caused by acute ischemic infarction or hemorrhage in the pituitary gland. "No evident correlation was found between expression levels of MMP9, MMP2, TIMP2, and PTTG1 and clinical features of PAs, including gender, age, compression symptoms, pituitary apoplexy, tumor texture, resection degree, and recurrence." (PMID 36052250, 2022). "The vascular endothelial growth factor, tumor necrosis factor-α (TNF-α), pituitary tumor-transforming gene (PTTG), matrix metalloproteinase-2/9 (MMP-2/9), proliferating marker (Ki-67), as well as hypoxia-inducing factor are the major contributing factors involved in pituitary apoplexy." (PMID 29615979, 2018).
plaque psoriasis (2 papers, 2006 to 2019). "For example, Infliximab is also used in the treatment of plaque psoriasis; we can replace the MMP-2/9 substrate linker with a marapsin substrate linker based on marapsin, which is a strongly up-regulated protease in psoriatic lesions." (PMID 31194726, 2019).
polycystic kidney (2 papers, 2020 to 2022). "Several studies on polycystic kidney disease have revealed cystic kidneys tubules synthesize and secrete high levels of MMPs, especially MMP-2, MMP-1 and MMP-9." (PMID 33256255, 2020).
polyp (2 papers, 2021 to 2023). A usually exophytic mass attached to the underlying tissue by a broad base or a thin stalk. "There was no MMP-2 and MMP-9 mRNA expression in polyp of vocal cord tissues." (PMID 31882379, 2021).
rectal tumor (2 papers, 2006 to 2014). "In both colon and rectal tumors, MMP-2, MMP-9 and TIMP-1 protein levels were higher than in corresponding paired normal mucosa, while TIMP-2 level in tumors was significantly lower than in normal mucosa." (PMID 16916471, 2006).
sarcopenia (2 papers, 2017 to 2020). Progressive decline in muscle mass due to aging which results in decreased functional capacity of muscles. "Although MMP-2 and MMP-9 seem to play major roles in the degradation of the extracellular matrix that leads to muscle wasting, the pathophysiological relevance of MMP-7 in the development and progression of sarcopenia is still mostly unknown." (PMID 32375664, 2020).
scleroderma (2 papers, 2023 to 2025). Scleroderma is a rare autoimmune connective tissue disorder characterized by abnormal hardening of the skin and, sometimes, other organs. "ADSCs may promote angiogenesis and especially lymphangiogenesis via VEGFD, MMP2, and Netrin 1, leading to revascularisation and normalisation of the disturbed microvascular architecture found in scleroderma." (PMID 37443817, 2023). "They identified NTN1, VEGFD, MMP2, FGF2, and FNDC5 as potential players in how the ADSCs secretome may disrupt vascular and perivascular inflammation hubs in scleroderma and thereby promote angiogenesis and lymphangiogenesis." (PMID 40584563, 2025). "The few effector molecules that were identified, including NTN1, VEGFD, MMP2, FGF2, and FNDC5, provide evidence for the anti-fibrotic and anti-inflammatory effects of the ADSC secretome; however, these few factors cannot explain all observed effects on scleroderma skin after autologous fat grafting." (PMID 37443817, 2023).
septic arthritis (2 papers, 2014 to 2016). "Although MMP-2 is not proposed to play a key role in arthritic cartilage degradation, high level of this enzyme was found in synovial fluid of horses with aseptic joint disease and septic arthritis." (PMID 27379277, 2014).
serous carcinoma (2 papers, 2016 to 2019). "Clearly, the stroma of a serous carcinoma stains positive for MMP-14 (1a) and negative for MMP-2 (1b)." (PMID 27038607, 2016).
Sjogren syndrome (2 papers, 2022 to 2024). An autoimmune disorder in which immune cells attack and destroy the glands that produce tears and saliva. "It is worth noting that we showed that inhibition of MMP-2 leads to increased tear production in an animal model of Sjogren’s syndrome dry eye disease." (PMID 36147586, 2022). "Furthermore, we reported that the inhibition of either JNK or MMP-2 activity restored tear secretion in animal models of Sjogren’s syndrome dry eye disease." (PMID 38984107, 2024). "These in vitro findings might explain the beneficial effects of inhibiting JNK or MMP-2 in chronically inflamed lacrimal glands of Sjogren’s syndrome dry eye disease animal models, resulting in increased tear production." (PMID 38984107, 2024).
Stillbirth (2 papers, 2011 to 2023). Death of the fetus in utero after at least 22 weeks of gestation. "Missense actin mutations in FLNB leading to atelosteogenesis type I and lethal skeletal dysplasia or inhibition of ERK/MMP-2 and MMP-9 pathways that are critical for trophoblast invasion, may be possible mechanisms of potentially lethal de novo FLNB SNVs in stillbirth etiology." (PMID 36800380, 2023).
synovial sarcoma (2 papers, 2013). "Synovial sarcoma was most sensitive to NM with block of MMP-2 at 500 μg/ml and MMP-9 at 100 μg/ml." (PMID 24085323, 2013). "Synovial sarcoma showed inhibition of MMP-2 with TNF-α and slight stimulation of MMP-9 at 10 ng/ml." (PMID 24085323, 2013). "Malignant synovial sarcoma cells did not secrete u-PA; however, MMP-2 and -9 secretions by SW-982 were inhibited by NM and secretion of TIMP-2 was enhanced by NM." (PMID 23661254, 2013).
T-cell acute lymphoblastic leukemia (2 papers, 2022 to 2025). Acute lymphoblastic leukemia of T-cell origin. "In patients with T-cell acute lymphoblastic leukemia (T-ALL), HIF-1α is overexpressed, and HIF-1α can promote the activation of Notch1 signaling, increase the expression of cyclin D1, CDK2, p21, MMP2, and MMP9 proteins, thereby leading to cell proliferation, invasion, and resistance." (PMID 35684364, 2022).
thymoma (2 papers, 2022 to 2023). A neoplasm arising from the epithelial cells of the thymus. "MMP-2 and MMP-7 are predominantly expressed in type B3 thymoma and thymic carcinoma, while MMP-9 is preferentially expressed in B2 thymomas." (PMID 38201593, 2023).
thyrotoxicosis (2 papers, 2012 to 2013). A hypermetabolic syndrome caused by the elevation of thyroid hormone levels in the serum. "Radioiodine therapy of thyrotoxicosis does not alter serum MMP-2, MMP-9 or TIMP-1 concentrations either acutely or after about three months of observation." (PMID 23107223, 2012). "In summary, our study demonstrates that radioiodine treatment of thyrotoxicosis does not alter serum MMP-2, MMP-9 or TIMP-1 concentrations, either acutely or after about three months of observation." (PMID 23107223, 2012).
urothelial carcinoma (2 papers, 2021 to 2022). A malignant neoplasm derived from the transitional epithelium of the urinary tract (urinary bladder, ureter, urethra, or renal pelvis). "MMP-2 and MMP-9 are associated with epirubicin resistance in urothelial carcinoma (UC)." (PMID 34654351, 2021).